LINC03171 (long independently transcribed non-coding RNA 3171)
Synonyms: uc.51
Gene: Long non-coding RNA gene on chromosome 2 (57,289,648 to 57,886,607, reverse strand). Ensembl gene ENSG00000285755.
Diseases named in the same sentence as LINC03171 in open-access papers:
LINC03171 is named in the same sentence as 2 diseases in open-access papers, as found by Europe PMC text mining. Sharing a sentence is not in itself a finding about the gene and the disease.
LINC03171 shares sentences with these, for which no sentence is quoted: dementia (1 paper); prediabetes (1).